MT1CP (metallothionein 1C, pseudogene)
Gene: Transcribed unprocessed pseudogene on chromosome 16 (56,648,248 to 56,649,514, forward strand). Ensembl gene ENSG00000205360.
Diseases named in the same sentence as MT1CP in open-access papers:
MT1CP is named in the same sentence as 2 diseases in open-access papers, as found by Europe PMC text mining. Sharing a sentence is not in itself a finding about the gene and the disease. The quoted sentences say what the papers report.
breast carcinoma (1 paper, 2022). "The roles of MT1CP, MT1L, and MT2A in HCC are still unknown, while MT2A could promote breast cancer invasiveness and might play a suppressive role in gastric cancer through inhibition of the NK-κB signaling pathway." (PMID 35300417, 2022).
MT1CP also shares sentences with these, for which no sentence is quoted: gastric cancer (1 paper).